BRCA2 (BRCA2 DNA repair associated)
Diseases named in the same sentence as BRCA2 in open-access papers (continued):
Sharing a sentence is not in itself a finding about the gene and the disease.
ovarian carcinoma (continued). "In women with a hereditary ovarian cancer syndrome the cumulative chance of developing ovarian cancer to the age of 80 years is 44% for BRCA1 and 17% for BRCA2 carriers." (PMID 34565426, 2021). "The ovarian cancer cluster regions (OCCR) largely overlap with the BRC repeats and the helical domain of BRCA2, whereas the breast cancer cluster regions (BCCR) cover both PALB2/EMSY-binding domains and DNA-binding domains." (PMID 34440403, 2021). "The ovarian cancer prospective cohort comprised 3152 BRCA1 carriers with 108 incident cases and 2495 BRCA2 carriers with 56 incident cases." (PMID 32665703, 2020). "We queried the OV-TCGA database and asked if ovarian cancer patients with low or high KAT5 expression showed any differences in survival, in BRCA2-mutant or BRCA2-wildtype backgrounds." (PMID 33257658, 2020). "All women with ovarian cancer are recommended to undergo germline genetic testing for BRCA1 and BRCA2 (Society for Gynecology Clinical Practice Statement 2014)." (PMID 32403357, 2020). "Preclinical studies and clinical trials in breast, ovarian cancer, and other cancers have shown the PARP inhibitors efficacy in BRCA1- and BRCA2-mutant patients." (PMID 32903519, 2020). "Bioinformatic analysis of the Australian Ovarian Cancer Study cohort (OV-AU) dataset suggests a higher incidence of NHEJ in ovarian tumors with low KAT5 expression, in both BRCA2-high and BRCA2-low backgrounds." (PMID 33257658, 2020). "Three of the four cases also diagnosed with ovarian cancer in cases were BRCA1/2 heterozygotes: one BRCA1 and two BRCA2 heterozygotes." (PMID 32300229, 2020). "Importantly, mono-allelic mutations in certain FA genes including FANCD1 (BRCA2), FANCS (BRCA1), FANCN (PALB2), FANCM, FANCJ (BRIP1), and FANCO (RAD51C) that are believed to operate downstream in the pathway and implicated in HR are associated with sporadic breast and ovarian cancer." (PMID 30813363, 2019). "There were 3 (2.2%) variant-positive females who had more than one cancer, all of whom had both breast and ovarian cancers: one with BRCA1 c.68_69delAG and two with BRCA2 c.5946delT." (PMID 31892343, 2019). "Germline mutations in these genes are associated with approximately 25% of the familial cases of breast and ovarian cancer and a significant proportion of sporadic cancers show BRCA1 and BRCA2 gene inactivation." (PMID 31273933, 2019). "PARP inhibition potentiated platinum cytotoxicity in the O-342/DDP and CH1cisR platinum-resistant ovarian cancer cell lines, as well as in the BRCAwt and BRCA2-restored OV90 and PEO4 ovarian cancer cell lines, respectively." (PMID 31080557, 2019). "This frequency was close to two multicenter studies from eastern and north China ovarian cancer patients by NGS 16.7% (13.1% in BRCA1 and 3.9% in BRCA2) and 28.4% (20.8% in BRCA1 and 7.6% in BRCA2), respectively." (PMID 30972954, 2019). "BRCA1 and BRCA2 germline mutations have been associated with approximately 25% of the familial cases of breast and ovarian cancer; therefore, BRCA1 and BRCA2 represent classical tumour suppressor genes." (PMID 31273933, 2019). "Since the frequency of BRCA-carriers was significantly lower, including cases with family history of breast or ovarian cancer, than in other regions, the study based on sequencing of whole BRCA1 and BRCA2 should be performed." (PMID 29492181, 2018). "In case of ovarian cancer, BRCA1 and BRCA2 patients exhibit a differential age of tumor development—BRCA1 carriers develop tumors earlier than those carrying BRCA2 mutations (48 vs. 57 years)." (PMID 29459887, 2018). "Molecular analysis of BRCA1 (MIM# 604370) and BRCA2 (MIM #600185) genes is essential for familial breast and ovarian cancer prevention and treatment." (PMID 30263092, 2018).
ovarian carcinoma (continued). "For ovarian cancer, the OC-PRS had a c of 0.58 (95% CI = 0.56 to 0.60) for BRCA1 carriers and a c of 0.63 (95% CI = 0.60 to 0.67) for BRCA2 carriers." (PMID 28376175, 2017). "Significant expression changes were also confirmed by RT-qPCR for some genes involved in homologous (HR) and non-homologous end joining (NHEJ) DNA damage-repair mechanisms in ovarian cancer, such as XRCC1 in EOC-CC1, and XRCC4, RAD51 and BRCA2 in OSPC2." (PMID 28482906, 2017). "According to previous studies on ovarian cancer biomarkers, FBN1 and MMP2 were found to be metastasis-promoting markers that were stimulated or suppressed by Aurora-A or BRCA2." (PMID 28562334, 2017). "The breast and ovary cancer cases were similar for both genes with 7 and 6 cases for BRCA1 and BRCA2, respectively, while the 3 cases of male breast cancer (one bilateral) presented a mutation only in BRCA2." (PMID 28947987, 2017). "Ovarian cancer was present in 6/10 families with the BRCA1 c.676delT (1 to 5 patients per family) and in 4/18 families with the BRCA2 c.7806-2A > G (1 to 3 patients per family)." (PMID 26852130, 2016). "The mean age of ovarian cancer diagnosis was 54.5 (range: 36–76), 58.4 (range: 51–76) and 61.9 (range: 40–81) years for BRCA1, BRCA2 and wild‐type patients, respectively." (PMID 27167707, 2016). "Other personal and familial history was notable for breast and ovarian cancer in both BRCA1 and BRCA2 patients." (PMID 27069714, 2016). "In 13 studies containing at least 60 families in which one or more cases of ovarian cancer were ascertained, the frequency of BRCA1 ranged from 24.2 to 76.2 % and the frequency of BRCA2 ranged from 1.0 to 16.7 %." (PMID 27004793, 2016). "As our study was limited by the inability to perform a comprehensive screen of both BRCA1 and BRCA2 due to cost limitations and the use of banked samples rather than a series, the overall frequency of mutation carriers in ovarian cancer cases not selected for cancer family history remains unknown." (PMID 25884701, 2015). "The findings from this study further define the spectrum and frequency of germline BRCA1/BRCA2 mutations in women with ovarian cancer not selected for family history of cancer and could further inform the development of mutation-screening policies for French Canadians in Quebec." (PMID 25884701, 2015). "Previously reported estrogen-dependent cancer genes including classical breast and ovarian cancer genes (e.g. BRCA1, BRCA2 and CHK2) as well as novel genes were scored in the screen." (PMID 25238049, 2014). "Patients with high-level expression of both BRCA2 and PRL in their ovarian cancers have a worse prognosis than those with high expression of BRCA2 or PRL alone in their ovarian cancers (with a HR of 1.43 versus a HR of 1.38 or 1.25 respectively)." (PMID 25344116, 2014). "These new high throughput testing methodologies, can detect multiple ovarian cancer biomarkers including focal amplifications of the HER2 and CCNE1 oncogenes, and somatic deletions of the BRCA1, BRCA2 genes in a single test." (PMID 23289505, 2013). "Nowadays, genetic testing is offered primarily to patients with early onset breast/ovarian cancer (<45 years) or when a strong family history is present, and it primarily involves analysis of BRCA1 and BRCA2 genes." (PMID 23536787, 2013). "Recently, a significantly higher mutation burden was detected by whole genome or exome sequencing in breast and ovarian cancer with mBRCA, compared with their counterparts carrying the wild-type BRCA1 and BRCA2 (wtBRCA) genes." (PMID 24265793, 2013). "In addition, upcoming trials of PARP inhibitors in ovarian cancer that specifically enrich for BRCA1 and BRCA2 carriers may be at particular risk for confounding biases in treatment response if differences in between these two biologically distinct groups are not considered." (PMID 24349831, 2013).
ovarian carcinoma (continued). "Besides the use of the MLPA, or other multiplex approaches, to test the effect of genetic variants predicted to affect splicing at the RNA level, it would be useful to test for BRCA1 and BRCA2 mutation negative patients with strong breast and/or ovarian cancer history." (PMID 22350158, 2012). "On the contrary, downregulation of BRCA2, a critical protein for homologous recombination repair (HRR), significantly enhanced the efficacy of cisplatin in killing ovarian cancer cell line PEO4." (PMID 21385444, 2011). "Research into the hereditary breast and ovarian cancer genes, breast cancer 1 (BRCA1) and BRCA2, is an area of ongoing discovery in the molecular biology of cancer." (PMID 22312502, 2011). "In women of Ashkenazi Jewish ascendance, up to 30% of breast and ovarian carcinomas may be attributable to mutations in these genes, where 3 founder mutations, c.68_69del (185delAG) and c.5266dup (5382insC) in BRCA1 and c.5946del (6174delT) in BRCA2, are commonly encountered." (PMID 22185575, 2011). "When comparing the study groups, the highest mutation detection rate in Slovenian population was observed in the families with at least one breast and at least one ovarian cancer (Group B) - 42% for BRCA1 and 8% for BRCA2 or 50% for both genes." (PMID 21232165, 2011). "The ovarian cancer SIR was 12.38 (3.1–49.51) for BRCA1 and the prostate cancer SIR was 18.55 (4.64–74.17) for BRCA2." (PMID 20877337, 2010). "Our data suggest that ovarian carcinomas maintain the coordinate regulation of BRCA1 and BRCA2 seen in normal tissues." (PMID 19602291, 2009). "We evaluated BRCA1, BRCA2, and MLH1 protein expression in 115 sporadic primary ovarian carcinomas, of which 31 had paired recurrent neoplasms collected after chemotherapy." (PMID 19602291, 2009). "MLH1, BRCA1, and BRCA2 protein expression was also assessed in 31 matched primary and recurrent ovarian carcinomas from the same patient to determine if chemotherapy influenced MLH1, BRCA1, or BRCA2 protein levels." (PMID 19602291, 2009). "As part of the model fitting, we have also re-estimated the breast and ovarian cancer risks in BRCA1 and BRCA2 carriers." (PMID 18349832, 2008). "We evaluated 49 ovarian carcinomas and categorized them according to pathology and BRCA1 and BRCA2 status." (PMID 18208621, 2008). "Germline mutations in BRCA1 (OMIM#113705, Online Mendelian Inheritance in Man) and BRCA2 (OMIM#600185) genes are responsible for an important fraction of hereditary breast and ovarian cancers." (PMID 17561994, 2007). "Original estimates of breast and ovarian cancer risks in carriers were based on the families used for positional cloning of the BRCA1 and BRCA2 genes, where all carriers had molecular testing, and all cancer diagnoses were validated." (PMID 17213823, 2007). "We chose SKOV-3 cells as a cellular model for ovarian cancer because in these cells the BRCA1 and BRCA2 genes, which are located next to the LASP-1 gene on chromosome 17q21, are upregulated." (PMID 17211471, 2007). "In BRCA2 carriers, the largest study is that of the BCLC which included data on 566 malignancies other than breast or ovarian cancers." (PMID 17213823, 2007). "The emerging picture is that breast and ovarian cancer risks in BRCA1 and BRCA2 carriers are substantially higher than in the general population, but that they are considerably affected by nongenetic, environmental factors, and by additional genetic modifiers." (PMID 17213823, 2007). "The ratio of breast to ovarian cancers is 2.39 : 1 for BRCA1 families and 6.18 : 1 for BRCA2 families, a difference which is significant at the 0.01% level by χ2 analysis." (PMID 12698193, 2003). "The ovarian cancer incidence rates in BRCA1 carriers rise to a peak in the 40–49 years age group, followed by a slight decline, while the BRCA2 ovarian cancer incidence rates were highest in the 50–59 year age group." (PMID 11857015, 2002).
ovarian carcinoma (continued). "We also allowed for separate ovarian cancer relative risks in the age groups 30–49, 50–59, and 60–69 years for BRCA1 and in the age groups 30–49 and 50–69 years for BRCA2." (PMID 11857015, 2002). "The relative risks of breast and ovarian cancer in BRCA1 and BRCA2 carriers, relative to the BCLC risks were all estimated to be less than one." (PMID 11857015, 2002). "In particular, risk factors are common and include age, family history of ovarian cancer, family history of breast cancer, a personal history of breast or ovarian cancer, BRCA1 or BRCA2 mutation, never having given birth, and estrogen hormone therapy." (PMID 41357196, 2025). "Most missense variants in the BRCA1, BRCA2, and ATM genes do not confer an increased risk of breast and ovarian cancer, but ones in specific domains do." (PMID 39858629, 2025). "SNRPB promotes ovarian cancer growth and metastasis by inhibiting POLA1 and BRCA2 exon 3 skipping." (PMID 39910288, 2025). "Another prominent result that showed up in both the EUR and non-EUR groups was between BRCA2 and ovarian cancer (EUR: p = 1.6 × 10−8, OR = 13; non-EUR: p = 1.0 × 10−5, OR = 33)." (PMID 39799398, 2025). "While using the DPP4 inhibitor sitagliptin had no additional benefit to olaparib in the Brca2-mutated model, it significantly impacted survival in the HRP ovarian cancer model." (PMID 40579444, 2025). "While patients with hereditary breast and ovarian cancer with germline double heterozygosity (GDH) for BRCA1 and BRCA2 are rare, carcinogenesis in these cases remains unclear." (PMID 40601170, 2025). "The most critical non-modifiable risk factors for ovarian cancer are germline mutations in BRCA1 and BRCA2." (PMID 41008855, 2025). "BRCA2 carriers were numerically more likely than non-carriers to have a first-degree relative with ovarian cancer (17% vs 3%, unadjp=0.0271, adjp=0.4336) and a first or second degree relative with any cancer (100% vs 73%, unadj.p=0.0056, adj.p=0.0952)." (PMID 40832411, 2025). "The ovarian cancer incidence by age 70 is 44%–59% in BRCA1 carriers and 17%–35% in BRCA2 carriers." (PMID 39907309, 2025). "In conclusion, it is crucial to continue exploring genetic risk factors for breast and ovarian cancers in individuals who do not have BRCA1 and BRCA2 mutations." (PMID 38660159, 2024). "Patients with this subtype of ovarian cancer who are negative for somatic mutations of the BRCA1 and BRCA2 genes will be subsequently tested for HRD (Homologous Recombination Deficiency) score evaluation." (PMID 38785549, 2024). "The second group included wild-type BRCA1 and BRCA2 controls (healthy individuals with benign gynecological diseases) and women with BRCA1 mutations but no ovarian cancer." (PMID 38877504, 2024). "Neither canonical nor noncanonical Wnt signaling was observed in BRCA2-null ovarian cancer cell in response to Wnt3A." (PMID 39028933, 2024). "Of 78 ovarian cancer patients with germline P/LP variants, 40 had BRCA1, 17 had BRCA2, and 22 had non-BRCA variants." (PMID 38355628, 2024). "In a clinical cohort of ovarian cancer, we show that the patients whose tumours have high levels of expression of MRE11 and low levels of expression of BRCA2 have poor rates of PFS, implying that targeting MRE11 could be clinically relevant." (PMID 37446144, 2023). "This weak evidence reflects the high percentage of HGSC in ovarian cancer, irrespective of the presence of germline BRCA1 and BRCA2 pathogenic variants." (PMID 37076566, 2023). "Although BRCA1 and BRCA2 work well for breast and ovarian cancers, they do not seem to be reliable for prostate cancer." (PMID 37444562, 2023).
ovarian carcinoma (continued). "Using this approach, we report that the BDP1 alterations identified in ovarian cancer were deep deletions with decreased expression correlating with increased serous ovarian cancer stage similar to known critical cancer drivers, BRCA1 and BRCA2." (PMID 36305848, 2023). "Apart from BRCA1, BRCA2 and MSH6, no clearly pathogenic variant was identified in other established ovarian cancer genes tested." (PMID 37013556, 2023). "In order to place our results within the context of clinical ovarian cancer, we analyzed existing TCGA datasets and asked whether expression of TGFB1 and BRCA2 were related." (PMID 37568736, 2023). "Inability to screen high-risk populations: Existing screening methods often do not identify ovarian cancer in high-risk populations, such as women with a family history of ovarian cancer or known genetic mutations like BRCA1 and BRCA2." (PMID 38084173, 2023). "Data for 10,373 ovarian cancer cases, including carriers and non-carriers of BRCA1 or BRCA2 pathogenic variants, were collected from unpublished international cohorts and consortia and published studies." (PMID 37076566, 2023). "The National Comprehensive Cancer Network (NCCN), American Society of Clinical Oncology (ASCO) as well as others, recommend germline BRCA1 and BRCA2 genetic testing for all epithelial ovarian cancer patients irrespective of histology." (PMID 37076566, 2023). "An earlier study has shown that BRCA2 does not pose a major threat in the development of ovarian cancer." (PMID 37110218, 2023). "Contrasting to the models of BRCA2-d, BRCA1-d in ovarian cancer was exclusively associated with clustered and non-clustered tandem duplications (1–10 kb)." (PMID 36883553, 2023). "Some studies have found a high frequency of VUS in HRR genes in ovarian cancer patients, but they have also shown that two decades of testing and research on BRCA1 and BRCA2 have led to a significant decrease in VUS rates in BRCA, which are lower than in most other genes." (PMID 36836518, 2023). "A better understanding of breast and ovarian cancer’s clinical features along with screening of BRCA1 and BRCA2 in the community may lead to timely diagnosis and management." (PMID 36197199, 2022). "In those families, the study consisted of 44 BRCA1 breast and/or ovarian cancer patients, 58 BRCA2 cancer patients, 602 non-BRCA patients and 328 other counselled patients." (PMID 35469032, 2022). "Women who test positive for an inherited pathogenic/likely pathogenic gene variant in BRCA1, BRCA2, PALB2, CHEK2 and ATM are at an increased risk of developing certain types of cancer—specifically breast (all) and epithelial ovarian cancer (only BRCA1, BRCA2, PALB2)." (PMID 35681696, 2022). "Preliminary in vitro data from our lab supports this hypothesis, as overexpression of MAGEC3 results in a reduction in BRCA2 protein level in both fibrosarcoma (HT1080) and ovarian cancer (SKOV3) cell lines." (PMID 36230652, 2022). "Within the last couple of days there was new information about BRCA women who had ovarian cancer (I think BRCA2 not sure) and new chemotherapy available for that." (PMID 35133282, 2022). "We describe germline whole-exome sequencing (WES) analyses and apply in silico predictive tools of familial ovarian cancer (OC) cases reported clinically negative for pathogenic BRCA1 and BRCA2 variants." (PMID 35456503, 2022). "In ovarian cancer, BRCA1 has 9.8% prevalence, followed by BRCA2 at 4.9%." (PMID 34979999, 2022). "Expression of this shorter BRCA2 isoform was not correlated with overall survival in 33 ovarian cancer patients after adjustment for patient recurrence status." (PMID 36344544, 2022). "Patients with ovarian cancer showed the next highest proportion (BRCA1: 4.86%; BRCA2: 3.42%)." (PMID 35420638, 2022). "Numerous studies have focused on the cancer risks of BRCA1 and BRCA2, but increased attention is needed to the multitude of non-BRCA mutations that impart ovarian cancer risk." (PMID 35159349, 2022).